MTOR (mechanistic target of rapamycin kinase)
Diseases named in the same sentence as MTOR in open-access papers (continued):
Sharing a sentence is not in itself a finding about the gene and the disease.
cancer (continued). "The reactivation of the PI3K or ERK pathway through the relief of the negative feedback loops in cancer cell lines, when treated with PI3K and/or mTOR inhibitors, has been well established." (PMID 33801977, 2021). "In recent years, many in vitro studies have shown that TGF-β induced EMT into non-tumour epithelial cells though the activation of mTOR and PI3K pathways, leading to the apoptosis resistance of cancer cells, thereby promoting the trans-differentiation of CAFs." (PMID 34830058, 2021). "In non-TNBC MCF-7 cancer cells, DHA treatment increased LKB1 activity, further increasing AMPK phosphorylation and mTOR inhibition." (PMID 33805447, 2021). "We predicted that the addition of both pharmacologic ascorbate and chloroquine is able to block both KRAS and mTOR pathways: in this case, no GLUT1 expression is observed, meanwhile autophagy, essential for KRAS mutant cancer cells, is blocked." (PMID 33925206, 2021). "We found that only a few types of cancer, such as THCA, THYM, and PRAD, had almost no CNV gains or CNV losses in mTOR pathway genes." (PMID 34194607, 2021). "Intriguingly, mTOR inhibitor efficacy was stronger in non-hypoxic conditions; nevertheless, the combination of the mTOR inhibitors with CAIX inhibitors portrayed anti-cancer activity under hypoxic conditions." (PMID 32272658, 2020). "BMS-754807 exerts a strong antineoplastic effect on several cancer model cells, apparently in a way mostly independent of IGF-1R inhibition and is able to inhibit the ERK1/2 and PI3K/AKT/mTOR signaling pathways, which are crucial for tumor cells to survive." (PMID 33322337, 2020). "Development of mTOR-dependent vulnerability in both Kras- and EGFR-mutant LUAD cells suggests that this phenotype could be a prevailing characteristic of chemotherapy-relapsed LUAD or MAPK-driven cancers in general, irrespective of the underlying pathway mutation." (PMID 32943635, 2020). "While active PI3K/AKT/MTOR signaling has a negative impact on the Hippo/MST activity, activation of the MEK/ERK signaling potentiates the induction of cancer cell death through the Hippo/MST signaling pathway." (PMID 32375238, 2020). "In addition, AMPK activation could induce apoptosis of ovarian cancer cells and delay endometrial cancer progression by inhibiting the mTOR and/or AKT pathways, which suggesting AMPK appears to serve as a tumor suppressor and exhibits an anti-cancer effect on genital system cancers." (PMID 33330475, 2020). "Some WTAP-related pathways have been proposed such as EGF signaling, the mTOR pathway or the WT1-TBL1 axis, while the involvement of WTAP as an m6A regulator in human cancers has not been explored previously." (PMID 31438961, 2019). "In spite of its extensive anti-cancer activities, OSU-53 does not significantly affect non-malignant MCF-10A cells, partially owing to the low basal activation levels of Akt/mTOR." (PMID 30791936, 2019). "In fact, PI3K/AKT/MTOR and JNK signaling are not independent pathways, but a complex network playing important biological roles in cancer and cooperating in the control of different events, including autophagy." (PMID 31261937, 2019). "In summary, except for CDKN2A, which is a clear outlier in the dataset under consideration, the changes in the local number of CNVs did not appear to be connected to the pan-cancer genes located in these regions (CAMTA1 and MTOR, MUC4 and TFRC, and NCOR2)." (PMID 31783642, 2019).
cancer (continued). "The metabolic remodelling in a tumour niche is endured not only by cancer cells but also by noncancerous cells that share the same microenvironment; in particular, macrophages seem to increase aerobic glycolysis via AKT/mTOR and HIF‐1α stabilization." (PMID 30499165, 2019). "We chose PI3K/MTOR signaling pathway inhibitors (PMSPIs), as PI3K/MTOR signaling pathway is a non-membrane tyrosine kinase pathway with a central role in cancer development." (PMID 31685861, 2019). "To explore BE503655-mediated potential molecular mechanism, we performed QT-PCR to screen signaling pathways, including mTOR, JNK and Wnt/β-catenin pathways, were confirmed to be mediated in human cancers (data were not shown)." (PMID 31316000, 2019). "Thus our study provide evidence that Ubtor constitutes a novel negative feedback mechanism to control mTOR signaling and cell growth, and manipulations of Ubtor function may potentially be utilized to optimize mTOR signaling activities for treatments of cancers and other diseases." (PMID 30080879, 2018). "In other types of cancer, the PI3K/AKT/mTOR pathway inhibitor-based therapies apparently failed to improve the OS." (PMID 29408858, 2018). "The mTOR target S6 (a serine/threonine kinase) has previously been shown to activate GLI1 in multiple cancer types, independent of SMO, indicating a crosstalk between the PI3K/AKT/mTOR- and Hh pathways." (PMID 28789624, 2017). "However, a previous study suggested that the potent growth inhibitory effects on cancer cells may not occur through this canonical mechanism of action and might involve direct binding of temsirolimus to mTOR leading to more robust inhibition of mTOR activity." (PMID 28926611, 2017). "Gene expression analysis revealed an interaction between sonidegib and 177Lu-octreotate, affecting several cancer-related signaling pathways (i.e. Wnt/β-catenin, PI3K/AKT/mTOR, G-protein coupled receptor, and Notch) not affected by either monotherapy." (PMID 28789624, 2017). "CSF2 activates AKT1-, ERK1/2-, mTOR- but not JAK/STAT-dependent signaling cascades, which are active in many cancer stem cells." (PMID 28031533, 2017). "Our hit list contains genes coding kinases with established oncogenic functions such as MET, EGFR, AKT, mTOR, RSK2 as well as genes that do not (yet) have an established role in cancer progression (NEK5, SIK2)." (PMID 27374095, 2016). "Recent studies investigating nutrient-signaling responses to Trp availability have identified independent roles for mechanistic target of rapamycin (mTOR) and general control non-derepressible 2 (GCN2) kinases in cancer cells." (PMID 27705910, 2016). "Two mTOR inhibitors, temsirolimus and everolimus, are already available for the clinical use, however their performance in BRCA-driven cancers has not been assessed yet in preclinical or clinical settings." (PMID 27555886, 2016). "Particularly, Gli-proteins are activated by EGF, K-RAS or mTOR in the absence of sonic hedgehog ligands and interact with the TGF-β signaling pathway in various malignant tumors." (PMID 27918595, 2016). "It has been shown recently that mTOR inhibitor rapamycin decreases lactate production in cancer cell lines regardless of normoxia or hypoxia, which may also extend our further anticancer investigation to target aerobic glycolytic adaptation to oncolytic viruses by mTOR inhibitors." (PMID 25575816, 2015). "PIK3CA mutations have been previously identified in several types of cancer, where they overactivate the PI3K/AKT/mTOR signaling in the absence of growth factors." (PMID 25915946, 2015). "From in vitro models, including PC12 cells transfected to overexpress BMP7, evidence was provided for non-canoncial signaling through the PI3K/Akt/mTOR pathway leading to overexpression of integrin β1, responsible for the BMP7-induced cancer phenotypes." (PMID 26793165, 2015). "As in cancer, the PI3K/Akt/mTOR pathway has a key role in promoting cell survival in the normal ovary." (PMID 23591839, 2013).
cancer (continued). "Starting from the metabolic state representing the typical traits of a cancer cell growing in condition of non-limiting glucose and modulating PI3K/Akt/mTOR activity, we obtained several metabolic steady states." (PMID 23181020, 2012). "Relevant studies have shown that the Akt/mTOR signaling pathway is a classical and important negative regulatory pathway for autophagy that the MAPK signaling pathway is involved in cancer development and progression through the regulation of cell apoptosis and autophagy." (PMID 41398772, 2025). "Moreover, the inhibition of mTOR triggers an unwanted negative feedback loop in which PI3K and AKT become activated, ultimately circumventing the anti-cancer activity of the mTOR blockade." (PMID 40723291, 2025). "TMG-mediated translation may be a missing piece for understanding protein synthesis in cells with little mTOR activity, including HIV-infected resting T cells and nonproliferating cancer cells." (PMID 40143300, 2025). "However,no reduction in human mTOR potency was observed for the tested compoundsrelative to sapanisertib (mTOR IC50 = 0.007 μM),the primary host target of sapanisertib for cancer treatment." (PMID 40377111, 2025). "Reports of dual PI3K/mTOR inhibitors (Gedatolisib, Omipalisib, Apitolisib, and others) currently in Phase I or II clinical stages indicate that none have received FDA approval for cancer therapy 96, 110-113." (PMID 40657399, 2025). "In addition, the three co-cultures expressed abundant levels of genes related to key cancer pathways, EGF and AKT/mTOR, with no obvious difference between the three cancer cell lines." (PMID 39011470, 2024). "While the mTOR inhibitor IDELALISIB, which is currently approved for the treatment of cancer with specific pharmacologic agents, has not been successful, inhibitors that inhibit both PI3K/mTOR have shown good results by inducing apoptosis as well as inhibiting autophagy." (PMID 39195222, 2024). "SPP1-related genes were mainly enriched in pathways related to cancer, immunoregulatory interactions between lymphoid and nonlymphoid cells, photodynamic therapy-induced NFkb survival signaling, focal adhesion PI3K, AKT, and the mTOR signaling pathway." (PMID 39042294, 2024). "Similarly, in another cancer type SCLS, we observed strong correlations (r ≥ 0.6)between predicted and observed metric values for similar drugs targeting the PI3K/MTOR pathway, but not for those drugs targeting the ERK/MAPK signalling pathway." (PMID 39304771, 2024). "While inhibition of mTOR, AKT and JNK pathways did not affect GM-CSF level, MEK1/2, ERK1/2, and ERK2 inhibitors hampered NrasG12D/PtenKO-derived GM-CSF secretion with no measurable effects on cancer cell proliferation." (PMID 38519484, 2024). "Although the relationship between β1 integrin and the components of the mTOR signaling pathway in NSC regulation has not been described, several studies suggest that β1 integrin expression and pAkt/Akt activity are in direct correlation, in cancer models." (PMID 38812794, 2024). "Our finding of upregulated AKT activation in CRC cells by the PP2A-B56γ3 holoenzyme was similar to the finding that cancer cells treated with mTOR inhibitors, such as rapamycin and Torin, exhibited hyperactivation of PI3K/AKT signaling by attenuating mTOR/p70S6K-mediated negative feedback loops." (PMID 37430297, 2023). "Although not explored, the mTOR signalling network was highly modified in docetaxel-treated TSO and can regulate both translational and metabolic machinery in cancer cells to regulate a cancer cell dormancy." (PMID 37703292, 2023). "Currently, the efficacy of mTOR inhibitors is limited in CRC, which may be related to the lack of study regarding MTOR function in this cancer type." (PMID 35883111, 2022). "Collectively, these data suggest that PI3K/AKT/mTOR or MAPK pathway is not involved in the PD‐mediated autophagy regulation in GBM cells, which was inconsistent with the previous results observed in other types of cancer cells." (PMID 33931944, 2022).
cancer (continued). "Further evidence showed that TGF-β–induced activation of mTOR and the PI3K–Akt pathway correlated with increased cell size and protein content in NMuMG mammary cells, supporting an important role for non-Smad TGF-β signaling pathway in cancer progression." (PMID 33499083, 2021). "Importantly, ER and HER2 were not strongly correlated with signalling effectors, suggesting that mTOR and/or MAPK activation are to some extent independent of the ER or HER2 status of individual cancer cells." (PMID 33790302, 2021). "When nutrients are lacking in cancer cells, MiT/TFE family of transcription factors can escape mTORC1-mediated negative regulation and locate in nucleus, thereby allowing cancer cells to maintain the activation of mTOR signaling and autophagy at the same time." (PMID 33292489, 2020). "However, the role of metformin in the control of neoplastic cancer cell growth is possibly independent of LKB-AMPK and mTOR." (PMID 33375360, 2020). "Similarly, drugs did not impact on mTOR S2448, VEGFR2 Y996, pERK T202/Y204 and Cyclin D1 expression levels in tumor counterparts while Tensirolimus reduced cancer organoid capacity formation." (PMID 30814510, 2019). "Inhibition of PI3K/mTOR using BEZ235 was able to prevent the initiation as well as the promotion to malignancy of carcinogen-induced SCC, but was not efficient against the established cancer." (PMID 30970654, 2019). "The findings suggest that the unintended activation of the PDK1/Akt/mTOR may be one reason why a potent PTKI such as ponatinb, despite its potent inhibition of its intended targets, may not work well against some cancers." (PMID 30959969, 2019). "For example, mammalian target of rapamycin (mTOR), downstream to the axis of receptor tyrosine kinase/PI3K/protein kinase B (AKT), which is frequently deregulated in cancer cells, is known to stimulate the expression of c-Myc and normoxic stabilization of HIF-1." (PMID 29468140, 2018). "Considering the major difference between two cancer cell lines is ERα that one expressed but another did not, we thought it may be a key factor mediating CPT inhibition of mTOR pathway." (PMID 28272775, 2017). "We revealed that cell growth of most human solid cancer cell lines we tested, but not non-cancer cell lines, can be inhibited by 1 T SMF at higher cell densities, in which the EGFR-Akt-mTOR pathway may play essential roles." (PMID 28061454, 2017). "However, the PI3K/AKT/mTOR pathway is not universally dysregulated across all cancers, and PAM inhibitors are only effective in cancers that rely on the PI3K/AKT/mTOR pathway as a driver." (PMID 26962408, 2016). "However, the relationship between aging, hypoxia and mTOR pathway is complex and additional studies are necessary to determine the specific interactions between HIF-1 and mTOR in non-transformed and cancer cells." (PMID 27280081, 2016). "The PI3K/AKT/MTOR and RAF/MEK/ERK signalling pathways are involved both in normal cell properties like regulation of cell proliferation and survival, as well as in the development of cancer." (PMID 26802026, 2016). "However, a comprehensive understanding of how PI3K/mTOR inhibitors target MYC proteins and a rationale for the selection of compounds likely to be clinically active against MYC-driven cancers is lacking." (PMID 27438153, 2016). "Moreover, we show that the regulatory activity of LARP1 is not just confined to mTOR, but that LARP1 is complexed to many other mRNA transcripts involved in cancer-related functions." (PMID 25531318, 2015). "We found that MMP-2 decreased by inhibiting CD44 via blocking mTOR signaling, whereas MMP-9 was not, demonstrating that the MMPs may have diverse roles in the signaling pathways of various cancers." (PMID 26202311, 2015). "However, it appears that according to the cell line tested, modulating calcium does not have the same consequence on AKT/mTOR and ERK activation which supports that calcium signaling is specific to cancer cells type." (PMID 25627260, 2015).
cancer (continued). "Further, aberrations in mTOR and AKT, though known to exist in cancer, were not assessed." (PMID 24742900, 2014). "How cancer cachexia may affect AMPK and PI3K/Akt/mTOR signaling in the heart has, to our knowledge, not been reported." (PMID 23589074, 2013). "Although they were not designed to evaluate cancer outcomes, the RMR study, the CONVERT study and the CONCEPT study all showed a reduced rate of malignancy development after conversion from a CNI to an mTOR inhibitor." (PMID 24565283, 2013). "Also in some cases it may be necessary to eliminate the cancer by treatment with a dual PI3K/mTOR inhibitor as well as with an additional PI3K inhibitor which suppresses the PI3K-p110-delta isoform as certain dual PI3K/mTOR inhibitors do not effectively suppress this isoform." (PMID 23085539, 2012). "In situations where complex I inhibition does not produce high amounts of ROS to damage a cancer cell's mitochondria, metformin's action through AMPK and mTOR may still allow growth inhibition to be achieved." (PMID 22781119, 2012). "In response to anti-cancer treatments, the RM_Score had a negative correlation (drug sensitive) with drugs that focused on the MAPK/ERK and metabolism signaling, and a positive correlation (drug resistant) with compounds targeting RKT and PI3K/mTOR signaling pathway." (PMID 36707911, 2023). "Key mechanisms in this process are also relevant to cancer incidence in the general population and not just in people with LFS, specifically, improvements in mitochondrial efficiency, reductions in chronic inflammation and oxidative stress, activation of AMPK and down-regulation of mTOR." (PMID 35406393, 2022). "Interestingly, inhibition of the mTOR pathway, but not the PI3K pathway, in triple-negative breast cancer cells led to increased FGF1 and Notch1 expression, enhanced FGFR1 activation and the formation of a resistant cancer stem cell-like population." (PMID 34830951, 2021). "However, other antagonists and agonists present in the screen including the 5-HTR4 agonists (Cisparide) that did not have any anti-cancer effects further suggesting that TM is uniquely acting to distinctly target other molecules, likely upstream receptors or kinases of the PI3K/Akt/mTOR pathways." (PMID 32085796, 2020). "Similarly, isogambogenic acid (2.5–10 μM) induced only autophagic cancer cell death and not apoptosis in human NSCLC cells (A549 and H460) and in a xenograft model (20 mg/kg, i.v., every 2 days, for 24 days), through the inhibition of the Akt/mTOR pathway." (PMID 32927836, 2020). "However, the activation status of mTOR (the catalytic subunit of mTORC1 and mTORC2) and upstream and downstream components of mTOR signaling in response to PGRN have not been well studied, especially in human cancer." (PMID 27517315, 2016). "Upstream of mTOR, the PI3K/AKT pathway is influenced by PTEN, the negative regulator of PI3K signaling, which decreases its expression in many cancers including pancreatic, and may be downregulated through several mechanisms including mutation, deletion, and methylation." (PMID 27200288, 2016). "As during progression of cancers selection operates favouring cells with activated oncogenes, it is not surprising that cells showing the activation of a HER2 downstream signal, such as mTOR, do not require the simultaneous activation of the upstream signal, i.e. HER2." (PMID 23587222, 2013). "Since there have been several case reports addressing the clinical efficacy of phenothiazine derivatives in cancer patients, the clinical use of thioridazine as a targeting agent of PI3K/Akt/mTOR signaling pathway may not be unrealistic when these concerns are resolved by further research." (PMID 22460505, 2012).